IL18 (interleukin 18)
Diseases named in the same sentence as IL18 in open-access papers (continued):
Sharing a sentence is not in itself a finding about the gene and the disease.
cancer (continued). "Therefore, IL-18 alone or in combination with other therapeutic drugs may hold a promising potential for cancer treatment." (PMID 28955343, 2017). "Moreover, IL-18 is a mediator of immune responses to eliminate cancer cells effectively." (PMID 28376875, 2017). "Therefore, it would be important to know whether IL-18BP level is sufficient to counteract the pleiotropic effects of IL-18 in the different stages and clinical conditions of cancer patients." (PMID 24963217, 2014). "In addition, an inappropriate production of IL-18 was found to contribute to the pathogenesis of cancers and may influence the clinical outcome of patients." (PMID 24223129, 2013). "Thus, the amino acid substitution of IL-18, which had a favorable energetic contribution and preserved the conformation of the protein compared to the native protein, may serve as a promising candidate for cytokine-based cancer drugs." (PMID 41154589, 2025). "Interleukin 18 (IL18), an 18-kilodalton cytokine, plays a complex role in cancer, exhibiting both anti-cancer and pro-cancer properties." (PMID 41257666, 2025). "The protumoral microenvironment is sustained by IL-33, IL-18, and PGD2, which are, at least in part, secreted by PCa cancer cells supporting the recruitment, proliferation, and function of ILC2s." (PMID 40247153, 2025). "In carcinoma patients, CRT-NP treatment enhanced MCP-1 serum levels whereas in STS patients GM-CSF, IL-2, IL-6 & IL-18 were enhanced." (PMID 40386779, 2025). "IL-18 has been shown to upregulate CD44, VEGF, and MMP-9 in an NF-κB-dependent manner, which increases cancer’s metastatic properties." (PMID 39451257, 2024). "Studies evaluating the expression of classic pro-inflammatory cytokines (TNF-α, IL-1β, IL-6, IL-17, IL-18, IL-33) in the spinal cord, PAG, and DRG revealed upregulation following inoculation of cancer cells to establish the BCP models." (PMID 38940936, 2024). "IL-18 KO mice showed reduced levels of IFN-γ and lower NK cell activity, leading to a diminished ability to combat pathogens and protect against cancer." (PMID 39769266, 2024). "The interaction between NLRP3 inflammasomes, inflammatory cytokines like IL-18 and IL-1b, and TNBC has been found to promote cancer development with the potential for novel anti-inflammasome treatments in this type of cancer." (PMID 39409110, 2024). "The expression of MISP, CHMP2B, IL-18, TMSB4X, and EFEMP1 proteins in carcinoma tissue was higher than that in para-carcinoma tissues." (PMID 38835670, 2024). "IL-1β, IL-18 and ASC, the pivotal elements of the inflammatory signaling pathway, are upregulated in breast cancer cells, but the specific cancer-promoting mechanism of NLRP1 inflammasomes needs to be further verified." (PMID 37020871, 2023). "The acidic microenvironment also modulated the interaction between cancer and immune cells through IFN-γ that was regulated by IL-18 and the NF-κB mediated pathway." (PMID 37719323, 2023). "Yet, several investigations have indicated that IL‐1β, IL‐18, and HMGB1 have a suppressive impact on cancer." (PMID 37752941, 2023). "The present investigation examined the effect of the acidic microenvironment generated by cancer cells on immune response in terms of expression of IFN-γ and IL-18." (PMID 37719323, 2023). "The cytokine IL-18 was regulated by RanBP1, and IL18 regulated cancer stem cell and EMT characteristics." (PMID 37047826, 2023). "Peripheral blood mononuclear cells supernatant also showed increased levels of IL-6, IL-8, IL-10, IL-18, macrophage inflammatory protein 1 gamma (MIP-1γ) (cancer-promoting) and TNF-α (cancer-suppressive)." (PMID 37681925, 2023). "IL-18 is a potent pro-inflammatory cytokine that acts as an IFN-γ-inducer factor in NK and T cells with effector cell lysis activity on cancer cells." (PMID 38298540, 2023).
cancer (continued). "When the inflammasomes are abnormally activated, a variety of inflammatory cytokines and chemokines, including TNF-α, IL-1β, IL-6, IL-18, CCL2/MCP-1, are excessively secreted, which affect the development of cancer." (PMID 37020871, 2023). "While IL18 alone can prime lymphocytes, IL18 combined with IL2 can promote the proliferation of NK cells, resulting in increased cytotoxicity against cancer." (PMID 38139000, 2023). "Numerous studies have demonstrated the efficacy of IL-18, IFN-γ and PH20 in cancer treatment, but the therapeutic potential of their combination has not been previously reported." (PMID 37513021, 2023). "When pyroptosis is activated, inflammatory mediators, such as IL‐1β, IL‐18, and HMGB1, are produced, all of which can have a positive impact on the progression of the cancer." (PMID 37752941, 2023). "Different cytokine-related pathways were upregulated in the stroma during the progression from normal mucosa to carcinoma, including interferon γ, interleukin (IL)-11, IL-10, IL-6, IL-9, IL1R and IL-18 signalling pathways." (PMID 36442992, 2023). "Overall, the NLRP3, PJVK, TIRAP, IL18, NLRP1 and NLRP6 genes were thought to protect against cancer, while the rest of the pyroptosis genes seemed to be correlated with cancer risk." (PMID 35246158, 2022). "The concomitant effects of IL-18, IL-1β and NLRP3 elevation were ignored in studies claiming that GSDMD mediates pyroptosis in cancer cells." (PMID 36091247, 2022). "Yet, the expression of IL18 is higher in U937 compared to NB4, while HL-60 cancer cells featured medium values." (PMID 35178376, 2022). "In endothelial cells, IL-18 upregulates VCAM-1, which enhances metastatic implantation and the spread of cancer cells." (PMID 36678726, 2022). "GSDMC, NLRP7, CASP5, PYCARD, IL18, IL1B and GSDMA were significantly upregulated in 22, 18, 18, 18, 18, 16 and 17 types of cancers, respectively." (PMID 35246158, 2022). "On the other hand, some inflammatory factors (IL-1β, IL18, and HMGB1) released by pyroptosis can trigger the activation of cancer-promoting signaling pathways including ERK1/2, p38 MAPK, and VEGF pathways." (PMID 35368686, 2022). "Even though IL-18 is considered an immunostimulatory cytokine, it presents an additive effect on regulatory functions of TGF-β1 in cancer model, affecting the cytolytic activity of NK cells." (PMID 35844531, 2022). "On the one hand, inflammatory factors released accompanying cancer cell pyroptosis form a chronic inflammatory microenvironment, including NLRP3, IL-18 and IL-1β." (PMID 36091247, 2022). "Compared with the human normal glial cell line (HEB), PLCG1, IL18, and IL6 were highly expressed in cancer cell lines (U251 and U87)." (PMID 36605437, 2022). "The induction of aerobic glycolysis by LMP1 leads to increased secretion of IL-1β, IL-6, IL-18, and GM-CSF, which in turn promotes MDSC differentiation and expansion as well as cancer cell proliferation and resistance to apoptosis." (PMID 33718235, 2021). "For instance, in vivo activation of NK cells using cytokine treatments (e.g., IL2, IL12, IL15, IL18 and IL21) has been investigated in several types of mouse cancer models and human cancers." (PMID 35008348, 2021). "The expression profile of IL-1β in the different tissues affected by cervical conditions was similar to that of IL-18, with a significant decrease in the mRNA expression levels between normal controls and cancer, as well as between LSIL and cancer." (PMID 31554368, 2019). "Thus, IL-18 had biological effects on the immune system and might be effective in treating cancer." (PMID 31492049, 2019). "Therefore, our data suggest that pMSCs could be used to treat cancers by enhancing the anti-cancer activity of NK cells in vitro through different mechanisms that would involve IL-12, IL-18, and IFN-ɣ receptors, as well as TLR3 and IL1ra as we previously suggested for DPMSCs." (PMID 30728068, 2019).
cancer (continued). "In contrast, poor prognosis in two types of cancer, LGG and PAAD, were correlated with high IL18 expression (Log-rank P < 0.05)." (PMID 31731729, 2019). "Our results showed a significant reduction in IL-18 expression between high grade lesions (HSIL) and cancer." (PMID 31554368, 2019). "Especially, pro-inflammatory cytokines such as IL-18, TNF-α, and IL-6 have a positive role in cancer progression, including cancer cell migration." (PMID 27589563, 2016). "The release of IL-18 and other TLR8-induced mediators augment NK cell activation signals in cancer patients." (PMID 26928328, 2016). "In skin injury models relevant to the development of cancer, irradiation with a physiological dose of UVB induced secretion of pro-IL-1α and of mature and active IL-1β and IL-18 in a caspase-1 dependent fashion." (PMID 26355424, 2015). "Additionally, IL-18 may serve as a valuable biomarker for certain types of cancer." (PMID 24273542, 2013). "In this context, our data reveals significant up-regulation of IL-18 and other pro-inflammatory cytokines in MSI-H cancers that promote Th1 activity." (PMID 15298707, 2004). "Agonists of the cytosolic double-stranded DNA-sensing stimulator of IFN gene (STING) pathway can mediate proinflammatory conversion of cancer MDSCs; however, secretion of the NLRP3 products IL-1β and IL-18 has also been observed in certain myeloid populations following STING activation." (PMID 40377974, 2025). "Unlike other types of cell death, pyroptosis in cancer cells has contradictory effects, as IL-18 and IL-1β are produced during the process of pyroptosis, inducing M2 polarization and cytotoxic T cells exhaustion." (PMID 41373022, 2025). "Recent findings indicate that caspase-3-mediated cleavage of IL-18 in cancer cells generates a truncated, nonsecreted form of IL-18 that translocates into the nucleus, where it facilitates STAT1 phosphorylation." (PMID 41087719, 2025). "Conclusively, Pereskia bleo leaves could potentially modulate the anti-cancer immune response by up-regulating IFN-γ, IL-12, IL-18, perforin, and granzyme B, while downregulating IL-8 and IL-10 in healthy blood samples." (PMID 39619199, 2024). "Two individual genes of module 6 were associated with treatment response, with IL18R1 being associated with good treatment response and IL1RAP being associated with poor response, in agreement with previous biological understanding of the IL18 and IL1 axes in cancer therapy." (PMID 38480759, 2024). "In addition, Leptin has been shown to upregulate the expression of IL-8 in M2 macrophages and IL-18 in TAMs, increase the expression of PLOD2, and promote the metastasis of cancer cells." (PMID 39192979, 2024). "IL-18 can also form a positive loop with interferon-γ (IFN-γ), which exerts a series of immune activities for cancer suppression, including the activation of cytotoxic T lymphocytes (CTLs), the production of granzyme B, and the inhibition of immunosuppressive cytokines." (PMID 39398428, 2024). "IL-18 warrants special attention in the context of chimeric antigen receptor T-cell (CAR T) therapy in which the patient’s own T cells are engineered and reprogrammed to destroy the patient’s cancer cells." (PMID 39769266, 2024). "Conversely, at lower doses and in the absence of IL12, IL18 exerts pro-cancer effects by inducing immune evasion and promoting angiogenesis." (PMID 38658734, 2024). "RP116 and IL-18/-21-pretreated eNK cells exhibited effective cytotoxicity against grade 1 carcinoma (5637 cells) when used alone, but not against HT-1376 (grade 2 carcinoma) and 253J-BV cells (derived from a metastatic site)." (PMID 38548803, 2024). "IL18 in combination with IL2 induces NK cells and has a cytotoxic role against cancers." (PMID 38139000, 2023). "We aimed to study whether PRV expressing IL-18, IFN-γ and PH20 could infect and kill cancer cell lines and promote antitumor immunity." (PMID 37513021, 2023).
cancer (continued). "Key events in this process are mediated by IL-1β and IL-18 signaling, as both cytokines accelerate the expression of vascular cell adhesion molecule 1 (VCAM1) in hepatic sinusoidal endothelial cells (HSECs), assisting the adhesion of cancer cells." (PMID 37891577, 2023). "These discrepancies may reflect the different roles of IL-1β/IL-18 and NLRP3 inflammasome in different cancer types or stages." (PMID 37715239, 2023). "Within this study, the drug-sensitivity analysis uncovered a negative correlation between the expression levels of the prognostic-related genes (PRGs) utilized in the model (IL18, CASP3, GSDMA, and PLCG1) and the majority of drugs present in the cancer therapeutic response portal database." (PMID 37561524, 2023). "Therefore, it is important to distinguish between the effects of IL-1β/IL-18 and the effects of NLRP3 inflammasome in cancer biology." (PMID 37715239, 2023). "Furthermore, IL-12, IL-15, and IL-18 induced CD25 and CD137 upregulation on CIML NK cells even after incubation with cancer cell lines (K562, HepG2, and SK-Hep-1 cells) after a 6-day interval." (PMID 36932395, 2023). "Extracellular ATP from cancer cells that undergo ICD mediates immune system chemotaxis by binding to purinergic receptor P2Y2 (P2RY2), and promoting the secretion of interleukin 1 β (IL-1β) and interleukin-18 (IL-18) by activating inflammatory corpuscles." (PMID 37153795, 2023). "Firstly, we analysed IL-18 expression in NSCLC tissues and para-carcinoma tissues." (PMID 37871286, 2023). "Significantly upregulated PRGs included PYCARD in 12 cancers; GSDMB in 10 cancers; IL18 in 9 cancers; GSDMD, CASP8, GZMB, and GPX4 in 8 cancers; AIM2 and CASP6 in 7 cancers; GZMA in 6 cancers; GSDME, CASP4 and DHX9 in 5 cancers; GSDMA and GSDMC in 4 cancers." (PMID 36605187, 2022). "According to the content of IL-1β, IL-6, IL-8, IL-18, and IL-10, the subgroup of luminal B (HER2-positive) cancer differed from the rest of the luminal subtypes, which suggested that it was HER2 status that was the determining factor influencing on the content of cytokines in saliva." (PMID 36286034, 2022). "In addition, Il18, Tnf, Ptgs2, Cd47, Cxcl1, and Csf1 were more highly expressed in STOSE tumors, including in the cancer cells, supporting the influence of TAMs in these tumors." (PMID 36311166, 2022). "In addition, we found that macrophage subpopulations (clusters 1, 5, 7, 8, and 9) from cancer tissues expressed a certain number of immunosuppressive genes, such as VEGFA, MMP14, MMP19, S100A2, APOE, HMOX1, SLAMF7, SIRPα, LAG3 and IL18." (PMID 36158683, 2022). "Pyroptosis-like immunogenic cell death (ICD) leads to the severe release of immunoregulatory molecules of IL-1β, IL-18, HMGB1, and ATP, and pyroptotic cancer cells were uptaken by antigen-presenting cells which suggested that pyroptosis were closely correlated to immune activity." (PMID 36281290, 2022). "Cancer cells secrete a number of angiogenicfactors (VEGF, EGF and interleukin-18)." (PMID 34455718, 2021). "Furthermore, the key genes correlated with KMO, such as the MYD88, IRF1, IL-18, and CASP1 genes, manipulate the inflammation where many cancers arise." (PMID 34683090, 2021). "Expression of IL18 was also increased in the VAT compared with the SAT in the cancer groups (CWS P = 0.03, CC P = 0.0006) but not in the control group (P = 0.9)." (PMID 32232960, 2020). "This was not linked to an intrinsic inability of intestinal ILCs to provide T-cell help, as in vitro IL-1β- and IL-18-stimulated ILCs from non-affected as well as cancer tissue readily upregulated HLA-DR and co-stimulatory molecules." (PMID 32341343, 2020). "After metastasis, pro‐inflammatory cytokines, including Il1α, Il1β, Il6, Il18, and TNF‐α, were significantly induced in lung metastases, indicating that inflammatory cytokines may play a positive role in cancer metastasis." (PMID 34766117, 2020).
cancer (continued). "With regard to the IL-18 expression profile in cervical tissues, the standardized relative quantities (NQRs) were 0.36 in normal samples; 0.56 in LSIL; 0.85 in HSIL and -0.43 in Cancer." (PMID 31554368, 2019). "That is to say, the contribution of -656 genotypes in human IL-18 to autoimmune diseases has started to be examined, but their involvement in any type of cancer has not." (PMID 30925760, 2019). "The balance between IL-1β and IL-18 may be cell-type, tissue, and context dependent, providing a possible explanation for the controversial role of the NLRP3 inflammasome in cancer." (PMID 31558756, 2019). "Considering the effect of macrophage CM on the upregulation of factors to increase vascular permeability, both M1 and M2 CM-treated cancer cells showed increased expression of angiopoietin-like 4 (ANGPTL-4), and M2-CM-treated cells expressed higher levels of IL-18." (PMID 30218063, 2018). "Some research studies have revealed that IL-18 has potential as an anti-cancer agent, however, this knowledge has not yet been successfully translated into the clinical practice." (PMID 27483370, 2016). "The majority of studies on serum IL-18 levels in cancer patients do not provide concomitant information about the concentration of its antagonist, that is, IL-18BP or IL-18-inducible cytokines such as IFN-γ in the same blood samples." (PMID 24963217, 2014). "In conclusion, gene therapy with IL-18 and HSV-TK plasmid vector driven by the hTERT promoter may be useful for cancer vaccination." (PMID 25051201, 2014). "In a clinical study of intravenous IL-18 dosing in patients with cancer, chills, and fevers were not common and were Grade 1 (low fevers)." (PMID 24115947, 2013). "For the purposes of the microarray data validation, we have selected 9 genes that may play the most important role in cancer cells-macrophages interactions: CCL2, CCL3, CD163, CSF1R, HIF1, Il-18, MMP9, VEGF-C, and Wnt7b." (PMID 22353646, 2012). "The ability of IL-18 to increase the ratio of effector CD8+ T cells to Tregs may have important implications for therapeutic vaccines and cancer therapy." (PMID 18818761, 2008). "Given its widespread immune-augmenting functions, it is not surprising that IL-18 has been evaluated in numerous animal models of cancer." (PMID 18818761, 2008). "Therefore, IL-18 and IFN-γ are promising candidates for the immunogene therapy of cancer." (PMID 37513021, 2023). "Indeed, there is an absence of the components of the NLRP3 inflammasome, IL-18 exacerbated cancer progression and inflammatory markers." (PMID 37298187, 2023). "Based on observations that IL-1β and IL-18 can contribute to AML anti-cancer drug resistance, and based on our data showing enhanced expression of PELI2 gene, mediating IL-1β and IL-18 activation may be a distinct plausible important mechanism by which PELI2 involved in emergence of drug resistance." (PMID 34127725, 2021). "AFP inhibits the maturation of dendritic cells (DC) and induces their apoptosis, so that antigens cannot be presented to T cells by DC cells, thereby freeing cancer cells from immune surveillance, indicating that IL‐18 does not participate in this cellular immune process." (PMID 33720453, 2021). "Although we have not yet formally tested the effects of IL-18 alone or IL-18+IL-12 in conjunction with NKT14m, future studies are warranted to explore these combination treatments to broaden the modalities for iNKT cell-based cellular immunotherapy for cancer." (PMID 32708464, 2020). "Subsequently, we investigated whether IL-2/IL-12/IL-18-pre-exposed γδ T cells in the absence of a TCR signal can drive cancer cells into senescence and terminal growth arrest, over time resulting in reduced impedances compared to control." (PMID 31947966, 2020). "While this study does not elucidate whether IL-18 or IL-1β induced production by anti-PD-L1 would be beneficial or detrimental for cancer treatment, it pinpoints an important discrepancy between anti-PD-1 and anti-PD-L1 mAbs." (PMID 33261061, 2020).